TIPE2 (TNF alpha induced protein 8 like 2)
Diseases named in the same sentence as TIPE2 in open-access papers (continued):
Sharing a sentence is not in itself a finding about the gene and the disease.
asthma (9 papers, 2017 to 2024). "Current studies have shown that TIPE2 is associated with the progression of lung injury, hepatitis, asthma, and other diseases." (PMID 37069964, 2023). "A total of 102 asthma patients who underwent sputum induction were enrolled to evaluate the expression level of TIPE2 and its association with different asthma phenotypes." (PMID 35572500, 2022). "Abnormal expression of TIPE2 may inhibit M1 macrophage‐associated neutrophilic inflammation in asthma by targeting the Nrf2/HMOX1 pathway." (PMID 39644500, 2024). "Intranasal administration of crocetin (100 μM/day, for 9-10 weeks) in OVA-induced asthma in mice, reduced the number of Treg cells and the levels of Foxp3 and TIPE2, indicating treatment properties of crocetin in asthma." (PMID 38419885, 2024). "TIPE2 is involved in M1 macrophage and M1 cytokine-mediated neutrophilic airway inflammation in asthma through activation of the Nrf2/HO-1 signaling pathway." (PMID 37069964, 2023). "TIPE2 in sputum of asthma patients positively correlated with pro-eosinophilic inflammation cytokines but negatively correlated with pro-neutrophilic inflammation cytokines." (PMID 35572500, 2022). "The result was consistent with down-regulated expression of TIPE2 in M1 macrophages that can release neutrophilic inflammation factors and aggravate neutrophilic inflammation in asthma." (PMID 35572500, 2022). "One study showed that TIPE2 levels in peripheral blood mononuclear cells (PBMCs) of asthma patients were lower than levels in healthy individuals and negatively correlated with eosinophil, IL-4, and IgE levels." (PMID 35572500, 2022). "Here, we sought to determine the expression pattern of TIPE2 in different asthma phenotypes and its relationship with neutrophilic and eosinophilic inflammation." (PMID 35572500, 2022). "Additional research will be required to elucidate the precise function of TIPE2 in each of these distinct asthma phenotypes." (PMID 35572500, 2022). "In contrast, our data showed that the TIPE2 level in sputum was comparable between asthma patients and healthy individuals." (PMID 35572500, 2022). "We next performed TIPE2 immunofluorescence analysis on sputum inflammatory cells from all asthma phenotypes." (PMID 35572500, 2022). "Tumor necrosis factor-α-induced protein 8-like 2 (TIPE2) has been found to be involved in the progression of asthma." (PMID 34446024, 2021). "Tumor necrosis factor-α-induced protein 8-like 2 (TIPE2) is a newly identified immune negative regulator that has been found to be involved in the progression of asthma." (PMID 34446024, 2021). "This study aimed to explore the role of TIPE2 in the regulation of airway smooth muscle cells (ASMCs), which are one of the main effector cells in the development of asthma." (PMID 34446024, 2021). "Our previous study showed TIPE2 mRNA and protein were both down-regulated in PBMCs of patients with childhood asthma." (PMID 28851386, 2017). "The heterogeneity of asthma airway inflammation or differences in asthma phenotypes could account for the disparities in TIPE2 levels in asthma patients." (PMID 35572500, 2022). "In this study, sputum TIPE2 levels were significantly increased in patients with EA and positively correlated with sputum IL-4, IL-5, and IL-13 that promoted eosinophilic inflammation in asthma." (PMID 35572500, 2022). "Abnormal expression of TIPE2 may play a regulator role in neutrophilic and eosinophilic inflammation in asthma." (PMID 35572500, 2022). "Although recent studies have highlighted the link of TIPE2 and asthma airway inflammation, its roles and molecular mechanisms in different asthma inflammatory phenotypes remain largely unknown." (PMID 35572500, 2022). "Aberrant expression of TIPE2 may target the Nrf2/HO-1 pathway to inhibit neutrophilic inflammation in asthma." (PMID 35572500, 2022). "We evaluated sputum TIPE2 expression level and its correlation with different asthma phenotypes." (PMID 35572500, 2022).
asthma (continued). "The sputum TIPE2 level was significantly lower in patients with neutrophilic asthma (NA) and higher in patients with eosinophilic asthma (EA) compared with patients with paucigranulocytic asthma." (PMID 35572500, 2022). "Thus, we assessed the correlation between sputum TIPE2 levels and cytokines that correlated with eosinophilic and neutrophilic inflammation in asthma." (PMID 35572500, 2022). "The heterogeneity of asthmatic airway inflammation and the variability of asthma phenotypes may contribute to the disparate roles of TIPE2 in asthma." (PMID 35572500, 2022). "The expression pattern of TIPE2 in asthma phenotypes may depend on the heterogeneity of airway inflammation." (PMID 35572500, 2022). "TIPE2 promoted the immune-suppressive effects of Tregs by increasing Foxp3 expression, thereby extenuating airway inflammation and airway hyperresponsiveness in the asthma mouse model." (PMID 35572500, 2022). "We speculate that TIPE2 may mediate the M1 polarization of macrophages by activating the Nrf2/HO-1 pathway to alleviate airway neutrophilic inflammation in asthma." (PMID 35572500, 2022). "TIPE2 may target Nrf2/HO-1 pathway activation to inhibit M1 macrophages inflammation, thereby mitigating airway neutrophilic inflammation in asthma." (PMID 35572500, 2022). "More researches needed to explore the role of TIPE2 in eosinophilic inflammation in asthma." (PMID 35572500, 2022). "Aberrant expression of TIPE2 may target the Nrf2/HO-1 pathway to inhibit M1 macrophage–related neutrophilic inflammation in asthma." (PMID 35572500, 2022). "TIPE2 mRNA and protein expression is decreased in children with asthma and negatively correlated with immunoglobulin E, eosinophil (EO), and interleukin-4 levels, suggesting that reduced TIPE2 expression may contribute to the pathogenesis of childhood asthma." (PMID 34446024, 2021). "Together, our results demonstrate an inhibitory role of TIPE2 on M1 inflammation through TIPE2 targeting Nrf2/HO-1 pathway activation and indicate that alterations in TIPE2 expression may lead to an interchange between the asthma inflammatory subtypes." (PMID 35572500, 2022). "However, another study found that TIPE2 may enhance the immune-suppressive activity of Tregs, thereby extenuating eosinophil accumulation in the airway and reducing the severity of asthma." (PMID 35572500, 2022). "However, the role of TIPE2 in asthma is complex and remains unclear." (PMID 35572500, 2022). "Therefore, TIPE2 may be related to airway inflammation in asthma." (PMID 35572500, 2022). "Thus, TIPE2 may be a potential therapeutic target for the treatment of asthma." (PMID 34446024, 2021).
breast cancer (8 papers, 2018 to 2024). A primary or metastatic malignant neoplasm involving the breast. "A study provided evidence to highlight that tumor necrosis factor-α-induced protein-8-like-2 (TIPE2) suppressed drug-induced autophagy, which sensitized breast cancer cells to PTX." (PMID 39539439, 2024). "TIPE2 was also downregulated in breast cancer cells, suggesting that TIPE2 can suppress the proliferation and migration of breast cancer cells." (PMID 36118167, 2022). "They showed that hydrodynamic gene delivery of TIPE2 plasmids in vivo resulted in the marked inhibition of breast cancer cells’ growth and metastasis." (PMID 31817720, 2019). "TIPE2, a negative regulator of innate as well as cellular immunity, was reported to be significantly downregulated in human breast cancer cells as well as tissues, and its overexpression inhibited the proliferation of tumor cells and tumor growth." (PMID 31817720, 2019). "For instance, one such study showed that TIPE2 prevented the migration and invasion of breast cancer cells through inhibition of β-catenin, cyclin D1, c-Myc, and epithelial-to-mesenchymal transition (EMT)." (PMID 31817720, 2019). "In contrast to our findings, TIPE2 was reported to block the proliferation, migration, invasion, and in vivo tumorigenesis in the case of breast cancer through the involvement of the Akt and p38 pathways." (PMID 31817720, 2019). "Further, TIPE2 was found to downregulate the expression of different proteins, such as β-catenin, cyclin D1, and c-Myc in breast cancer cells." (PMID 31817720, 2019). "In the case of another study, TIPE2 overexpression was reported to notably inhibit the proliferation of breast cancer cells." (PMID 31817720, 2019). "Breast cancer cells treated with PTX showed increased expression of the autophagy-associated proteins Beclin1 and LC3B (LC3II/I), but these proteins were down-regulated when TIPE2 was overexpressed." (PMID 39539439, 2024). "TIPE2 up-regulated production of CD8+ T and natural killer (NK) cells, and inhibited breast cancer development and metastasis." (PMID 33817189, 2019). "TIPE2 suppresses the proliferation and tumorigenesis by inhibiting β-catenin, cyclin D1 and c-Myc, and metastasis via AKT and p38 signaling pathways in breast cancer." (PMID 30157801, 2018). "For example, in breast cancer (BC), tumor necrosis factor–α (TNF-α)–induced protein-8 like-2 (TIPE2) fosters the production of interferon-γ (IFN-γ) and TNF-α by NK cells, enhances the killing ability of NK cells to BC cells, and hampers the development and metastasis of BC." (PMID 38073330, 2024).
lung carcinoma (8 papers, 2015 to 2025). "As tobacco is the most predominant risk factor for lung cancer, we therefore evaluated the effect of TIPE2 in tobacco-mediated lung carcinogenesis as well." (PMID 31817720, 2019). "The results showed that loss of TIPE2 effectively reduced the migration potential of lung cancer cells." (PMID 31817720, 2019). "In this study, we also found that knockout of TIPE2 resulted in the downregulation of Akt/mTOR, S6, and NF-κB signaling and their downstream targets, which are involved in diverse cellular processes linked with lung cancer." (PMID 31817720, 2019). "In addition, we elucidated the role of TIPE2 on different regulatory processes in lung cancer and underlined molecular mechanism of action." (PMID 31817720, 2019). "Therefore, it is imperative to decipher the associated signaling molecules/pathways to unravel the underlined molecular mechanism of action of TIPE2 in lung cancer cells." (PMID 31817720, 2019). "In addition, knockout of TIPE2 also caused arrest in the S phase of the cell cycle of lung cancer cells." (PMID 31817720, 2019). "The results demonstrated that TIPE2 was down-regulated in some histological subtypes of lung cancer, which encouraged us to further inquire into the specific role and underlying mechanism of TIPE2 in lung cancer development." (PMID 25946186, 2015). "Therefore, we evaluated the association between this signaling axis and TIPE2-mediated lung cancer." (PMID 31817720, 2019). "Targeting TIPE2 highlights a previously overlooked strategy synergistical with ferroptosis induction and PD-L1 blockade in melanoma and lung carcinoma." (PMID 39851538, 2025). "For determining the effect of nicotine, NNK, NNN, and BaP on the clonogenic potential of NCIH460 lung cancer cells after knockout of TIPE2, a colony formation assay was performed." (PMID 31817720, 2019). "Further, this is the first report which shows the correlation between tobacco constituents and the regulation of TIPE2 in human lung cancer." (PMID 31817720, 2019). "We found that TIPE2 plays a pivotal role in different processes of lung cancer development, such as survival, proliferation, invasion, and migration." (PMID 31817720, 2019). "Immunohistochemical analysis showed that TIPE2 was significantly upregulated in different stages and grades of lung cancer tissues compared to normal lung tissues, implying its involvement in the positive regulation of lung cancer." (PMID 31817720, 2019). "In the case of cell cycle analysis, we found that knockout of TIPE2 led to an increase in the number of cells in S phase compared to CRISPR/Cas9 scramble lung cancer cells." (PMID 31817720, 2019). "The findings of our previous studies showed TIPE2 to have a profound role in the promotion of lung cancer cell proliferation, survival, and migration." (PMID 31817720, 2019). "Further, we observed TIPE2 to be involved in inducing proliferation, survival, and migration of lung cancer cells." (PMID 31817720, 2019). "Further, knockout of TIPE2 resulted in significantly reduced proliferation, survival, and migration of human lung cancer cells through modulation of the Akt/mTOR/NF-κB signaling axis." (PMID 31817720, 2019). "To understand the role of TIPE2 in lung cancer, we initially analyzed the expression of TIPE2 in lung cancer tissues." (PMID 31817720, 2019). "In order to see the effect of nicotine, NNK, NNN, and BaP on the proliferation of NCIH460 human lung cancer cells after knockout TIPE2, the MTT assay was performed." (PMID 31817720, 2019). "Initially, we determined the expression of TIPE2 in lung cancer tissues through immunohistochemical analysis of TMA slides containing tissues of different lung cancer pathologies, stages, and grades." (PMID 31817720, 2019). "The results showed that knockout of TIPE2 led to the reduced clonogenic potential of NCIH460 cells compared to the scrambled control, implying the involvement of TIPE2 in increasing the survival of lung cancer cells." (PMID 31817720, 2019).
lung carcinoma (continued). "In the present study, we evaluated the expression of TIPE2 in lung cancer tissues and its role in different processes involved in the development and progression of lung cancer." (PMID 31817720, 2019). "Taken together, TIPE2 plays a critical role in the development and progression of lung cancer and also in tobacco-promoted lung carcinogenesis." (PMID 31817720, 2019). "The arrest in the S phase of the cell cycle suggested that knockout of TIPE2 plausibly led to the apoptosis of lung cancer cells." (PMID 31817720, 2019). "Our analysis revealed that TIPE2 was significantly upregulated in lung cancer tissues compared to normal lung tissues." (PMID 31817720, 2019). "Taken together, TIPE2 possesses an important role in the development and progression of lung cancer, particularly in tobacco-promoted lung cancer, and hence, specific targeting of it holds an enormous prospect in newer therapeutic interventions in lung cancer." (PMID 31817720, 2019). "Further, in our study, TIPE2 showed upregulation in different pathologies of lung cancer, such as adenocarcinoma, squamous cell carcinoma, adenosquamous carcinoma, and large cell carcinoma compared to normal lung tissues." (PMID 31817720, 2019). "Our analysis revealed TIPE2 to be significantly upregulated in lung cancer tissues when compared to normal lung tissues." (PMID 31817720, 2019). "Further, TIPE2 promoted lung cancer cell apoptosis via modulation of caspase-3, -9, Bcl-2, and Bax through the P38 and Akt pathways." (PMID 31817720, 2019). "Overexpression of TIPE2 significantly inhibited the growth of lung cancer cell H446 in vitro and even suppressed tumor formation in vivo." (PMID 25946186, 2015). "In lung cancer tissues, TIPE2 showed strong staining in primary lung adenocarcinoma and lymph node metastasis tissue, but exhibited very weak staining in lung squamous cancer and even almost no staining in most of small cell lung cancer." (PMID 25946186, 2015). "To investigate the potential biological function of TIPE2 in lung cancer, we examined the effects of TIPE2 on cell growth of lung cancer cell H446 by MTT assay and colony formation assay, and apoptosis by flow cytometric." (PMID 25946186, 2015). "Interestingly, a considerable volume of literature has reported that TIPE2 performs a critical role in tumorigenesis; several types of tumors can be suppressed by TIPE2 expression e.g. hepatocellular, prostatic, and lung cancer." (PMID 40060230, 2025). "Also, lung cancer patients with TIPE2 high-level expression in MDSCs had poorer long-term survival than the ones with TIPE2 low-level expression in MDSCs." (PMID 39851538, 2025). "However, contrary to our findings, overexpression of TIPE2 was reported to be negatively correlated with the advanced clinical stage of lung cancer." (PMID 31817720, 2019). "Therefore, in order to know the involvement of TIPE2 in the modulation of the migration of lung cancer cells, the wound healing assay was performed." (PMID 31817720, 2019). "In addition, a study conducted by Liu and colleagues evaluated the expression of TIPE2 in the tissues of different lung cancer pathologies, such as lung squamous cancer, small cell lung cancer, and lung adenocarcinoma." (PMID 31817720, 2019). "In addition, TIPE2 was found to be upregulated in different stages of lung cancer, such as stage I, II, and IIIa, and also in different grades of lung tumor, such as grade 1, 2, and 3, compared to normal lung tissues." (PMID 31817720, 2019). "Therefore, we evaluated the effect of nicotine, NNK, NNN, and BaP on the proliferation, survival, and migration of NCIH460 human lung cancer cells after knockout of TIPE2." (PMID 31817720, 2019). "Altogether, we found TIPE2 to play a vital role in tobacco-promoted lung cancer and therefore, specific targeting of it holds enormous prospect in newer therapeutic interventions in lung cancer." (PMID 31817720, 2019).